SWSAP1 (SWIM-type zinc finger 7 associated protein 1)
Description:
Single-stranded DNA-stimulated ATPase involved in DNA double-strand break (DSB) repair via homologous recombination (HR). Forms a heterodimeric complex with ZSWIM7/SWS1 that promotes HR by regulating replication protein-A (RPA) dynamics on single-stranded DNA, thereby stabilizing RAD51 and DMC1 filaments on DNA. The SWSAP1-ZSWIM7/SWS1 heterodimer is essential during meiosis by stabilizing DMC1 filaments (By similarity). In contrast, it is critical for only certain types of homologous-directed DNA repair, such as inter-homolog homologous recombination (IR-HR). IR-HR is a DNA repair mechanism where a cell repairs a DSB on one chromosome using the matching homologous chromosome as a template, rather than the sister chromatid. Also promotes homologous recombination by inactivating the FIGNL1-FIRRM complex to protect RAD51 filament from premature disassembly. Has a DNA-binding activity which is independent of its ATPase activity: preferentially binds DNA with an exposed 5' end.
Synonyms: ZSWIM7AP1; C19orf39; FLJ35119; SWS1AP1
Tractability: No criterion of Open Targets' tractability assessment is met for any kind of drug.
Gene: Protein-coding gene on chromosome 19 (11,374,666 to 11,376,951, forward strand). Ensembl gene ENSG00000173928.
Subcellular location: Chromosome; Nucleus
Subcellular location (Human Protein Atlas): Nucleoplasm; Cytosol
Gene Ontology:
Molecular function: ATP hydrolysis activity; molecular function inhibitor activity; protein binding; single-stranded DNA binding
Biological process: DNA recombinase assembly; double-strand break repair via homologous recombination; protein stabilization
Cellular component: Shu complex; chromosome; nucleus
Genetic constraint (gnomAD): Loss-of-function variants: 5 observed, 6.84 expected, observed/expected ratio (o/e) 0.73, 90% interval 0.38 to 1.51. That is too few expected variants to judge how well the gene tolerates losing a copy. Missense variants: 351 observed, 337.18 expected, observed/expected ratio (o/e) 1.04, 90% interval 0.95 to 1.14. Synonymous variants: 139 observed, 151.64 expected, observed/expected ratio (o/e) 0.92, 90% interval 0.8 to 1.05.
Homologues: Orthologues: chimpanzee SWSAP1 (99% identical), macaque SWSAP1 (97% identical), pig SWSAP1 (78% identical), rabbit SWSAP1 (72% identical), guinea pig SWSAP1 (71% identical), rat Swsap1 (68% identical), mouse Swsap1 (67% identical), tropical clawed frog swsap1 (35% identical).
Diseases named in the same sentence as SWSAP1 in open-access papers:
SWSAP1 is named in the same sentence as 6 diseases in open-access papers, as found by Europe PMC text mining. Sharing a sentence is not in itself a finding about the gene and the disease. The quoted sentences say what the papers report.
infertile (2 papers, 2018 to 2022). "Zswim7 (Sws1)/Swsap1 mutant mice reproduce the infertility phenotype, demonstrating marked meiotic abnormalities." (PMID 34402903, 2022).
Bloom syndrome (1 paper, 2021). Bloom syndrome (BSyn) is a rare chromosomal breakage syndrome characterized by a marked genetic instability associated with pre- and postnatal growth retardation, facial sun-sensitive telangiectatic erythema, increased susceptibility to infections, and predisposition to cancer. "The relevance of these genetic interactions is evident as SWSAP1 loss prolongs Blm-mutant embryo survival, suggesting a possible druggable target for the treatment of Bloom syndrome." (PMID 34253720, 2021).
Fanconi anemia (1 paper, 2019). Fanconi anemia (FA) is a hereditary DNA repair disorder characterized by progressive pancytopenia with bone marrow failure, variable congenital malformations and predisposition to develop hematological or solid tumors. "However, the MMC sensitivity observed in sgSWS1 and sgSWSAP1 cells is modest compared with disruption of members of the Fanconi anemia pathway such as FANCD2 and is comparable to what is observed in Swsap1−/− mouse fibroblasts." (PMID 31665741, 2019).
ovarian carcinoma (1 paper, 2018). A malignant neoplasm originating from the surface ovarian epithelium. "Mutations in the human RAD51 paralogs (RAD51B, RAD51C, RAD51D, XRCC2, XRCC3, and SWSAP1) are found in a subset of breast and ovarian cancers." (PMID 30551670, 2018).
cancer (4 papers, 2018 to 2025). A tumor composed of atypical neoplastic, often pleomorphic cells that invade other tissues. "Here, we focused on the human RAD51 paralogs—RAD51B, C, D, XRCC2, 3, and SWSAP1—and explored their known and emerging functions, the challenges in further uncovering their roles, and their association with cancer predisposition." (PMID 30551670, 2018).
SWSAP1 also shares sentences with these, for which no sentence is quoted: female reproductive diseases (1 paper).